COX8C (cytochrome c oxidase subunit 8C)
Description:
Component of the cytochrome c oxidase, the last enzyme in the mitochondrial electron transport chain which drives oxidative phosphorylation. The respiratory chain contains 3 multisubunit complexes succinate dehydrogenase (complex II, CII), ubiquinol-cytochrome c oxidoreductase (cytochrome b-c1 complex, complex III, CIII) and cytochrome c oxidase (complex IV, CIV), that cooperate to transfer electrons derived from NADH and succinate to molecular oxygen, creating an electrochemical gradient over the inner membrane that drives transmembrane transport and the ATP synthase. Cytochrome c oxidase is the component of the respiratory chain that catalyzes the reduction of oxygen to water. Electrons originating from reduced cytochrome c in the intermembrane space (IMS) are transferred via the dinuclear copper A center (CU(A)) of subunit 2 and heme A of subunit 1 to the active site in subunit 1, a binuclear center (BNC) formed by heme A3 and copper B (CU(B)). The BNC reduces molecular oxygen to 2 water molecules using 4 electrons from cytochrome c in the IMS and 4 protons from the mitochondrial matrix.
Synonyms: COX8-3
Tractability: Antibody: UniProt predicts a signal peptide or a membrane-spanning region.
Gene: Protein-coding gene on chromosome 14 (93,347,182 to 93,348,356, forward strand). Ensembl gene ENSG00000187581.
Subcellular location: Mitochondrion inner membrane
Pathways (Reactome):
Metabolism: Complex IV assembly; Respiratory electron transport
Cellular responses to stimuli: Cytoprotection by HMOX1
Gene Ontology:
Biological process: mitochondrial electron transport, cytochrome c to oxygen; oxidative phosphorylation
Cellular component: mitochondrion; mitochondrial inner membrane; respiratory chain complex IV
Genetic constraint (gnomAD): Loss-of-function variants: 1 observed, 1.17 expected, observed/expected ratio (o/e) 0.85, 90% interval 0.24 to 1.88. That is too few expected variants to judge how well the gene tolerates losing a copy. Missense variants: 81 observed, 55.89 expected, observed/expected ratio (o/e) 1.45, 90% interval 1.21 to 1.74. Synonymous variants: 36 observed, 23.93 expected, observed/expected ratio (o/e) 1.5, 90% interval 1.15 to 1.89.
Homologues: Orthologues: chimpanzee COX8C (100% identical), rabbit COX8C (51% identical), pig COX8H (32% identical), rat Cox8b (28% identical), mouse Cox8b (26% identical), zebrafish cox8a (24% identical). Paralogues in human: COX8A (31% identical).
Diseases named in the same sentence as COX8C in open-access papers:
COX8C is named in the same sentence as 5 diseases in open-access papers, as found by Europe PMC text mining. Sharing a sentence is not in itself a finding about the gene and the disease. The quoted sentences say what the papers report.
breast carcinoma (1 paper, 2025). "By contrast, COX8C has not yet been functionally linked to breast cancer pathogenesis." (PMID 41157129, 2025).
epithelial ovarian cancer (1 paper, 2017). "In the meanwhile, the alterations of COX8C is associated with epithelial ovarian cancer risk and KIAA1409 is a tumor suppressor gene." (PMID 29322932, 2017).
tumor (3 papers, 2012 to 2025). "Importantly, however, the interrogation of the DEPC 3.0 database showed that nearly all of the identified proteins, with the exception of only three (COX16, NDUFB2, COX8C), are consistently annotated as being altered during tumor dissemination and metastatic progression." (PMID 41157129, 2025).
adenocarcinoma (1 paper, 2025). A common cancer characterized by the presence of malignant glandular cells. "Other studies support our data showing mitochondrial energy metabolism gene expression varies between the metaplasia to adenocarcinoma disease sequence with some genes decreasing (ATP12A, COX4I2) and others increasing (COX8C)." (PMID 40381373, 2025).
COX8C also shares sentences with these, for which no sentence is quoted: Barrett esophagus (1 paper).